PCTP (phosphatidylcholine transfer protein)
Description:
Catalyzes the transfer of phosphatidylcholine between membranes. Binds a single lipid molecule.
Synonyms: PC-TP; StARD2
Tractability: Small molecule: a structure with a bound ligand is known; a high-quality ligand is known; it has a high-quality binding pocket. PROTAC: a small molecule that binds it is known.
Gene: Protein-coding gene on chromosome 17 (55,751,051 to 55,842,830, forward strand). Ensembl gene ENSG00000141179.
Subcellular location: Cytoplasm, cytosol
Subcellular location (Human Protein Atlas): Nucleoli; Nucleoplasm
Pathways (Reactome):
Metabolism: Mitochondrial Fatty Acid Beta-Oxidation; Synthesis of PC
Gene Ontology:
Molecular function: phosphatidylcholine binding; phosphatidylcholine transporter activity; protein binding; lipid binding
Biological process: phospholipid transport; lipid transport; negative regulation of cold-induced thermogenesis; phosphatidylcholine biosynthetic process; lipid metabolic process; lipid translocation
Cellular component: cytosol
Genetic constraint (gnomAD): Loss-of-function variants: 18 observed, 17.67 expected, observed/expected ratio (o/e) 1.02, 90% interval 0.7 to 1.51. The upper end of that interval is the gene's LOEUF score, 1.51, which puts it in group 6 of 6, group 1 being the genes least tolerant of losing a copy. Missense variants: 225 observed, 202.8 expected, observed/expected ratio (o/e) 1.11, 90% interval 0.99 to 1.24. Synonymous variants: 83 observed, 77.16 expected, observed/expected ratio (o/e) 1.08, 90% interval 0.9 to 1.29.
Homologues: Orthologues: chimpanzee PCTP (91% identical), macaque PCTP (88% identical), rabbit PCTP (87% identical), mouse Pctp (81% identical), rat Pctp (79% identical), guinea pig PCTP (79% identical), zebrafish pctp (60% identical). Paralogues in human: STARD7 (28% identical), STARD10 (25% identical).
Diseases named in the same sentence as PCTP in open-access papers:
PCTP is named in the same sentence as 9 diseases in open-access papers, as found by Europe PMC text mining. Sharing a sentence is not in itself a finding about the gene and the disease. The quoted sentences say what the papers report.
steatosis (2 papers, 2020 to 2023). Increased lipid within the cytoplasm of cells. "PCTP might function within the hepatocyte to redistribute PCs from the endoplasmic reticulum to lipid droplets thus regulating lipid droplet morphology and favoring microvesicular steatosis." (PMID 32213983, 2020).
sarcopenia (1 paper, 2026). Progressive decline in muscle mass due to aging which results in decreased functional capacity of muscles. "In contrast, sarcopenia group showed remarkably reduced PCTP (P < 0.001), SREBF2 (P < 0.001), and PPARGC1A (P < 0.05) levels." (PMID 41460756, 2026). "The qPCR results demonstrated that FABP3 (P < 0.001), PECR (P < 0.01), and OPN3 (P < 0.001) expression markedly increased in D‐gal‐induced sarcopenia compared with control groups, whereas PCTP (P < 0.001), SREBF2 (P < 0.001), and PPARGC1A (P < 0.05) levels dramatically decreased." (PMID 41460756, 2026).
cancer (3 papers, 2011 to 2023). A tumor composed of atypical neoplastic, often pleomorphic cells that invade other tissues. "To date, the function of PCTP and IDI1 in the progression of cancers is still unclear, and further experimental work is needed." (PMID 36826154, 2023).
PCTP also shares sentences with these, for which no sentence is quoted: atypical hemolytic-uremic syndrome (1 paper); breast carcinoma (1); cystic fibrosis (1); microangiopathic hemolytic anemia (1); renal failure (1); Thrombocytopenia (1).